NTN4 (netrin 4)
Diseases named in the same sentence as NTN4 in open-access papers (continued):
Sharing a sentence is not in itself a finding about the gene and the disease.
invasive breast carcinoma (1 paper, 2022). A carcinoma that infiltrates the breast parenchyma. "In invasive breast carcinoma, NTN4 expression is associated with longer DFS and OS, as an independent prognostic factor affecting survival." (PMID 35732855, 2022). "NTN4 expression was significantly lower in invasive breast carcinoma compared with adjacent non-malignant tissues." (PMID 35732855, 2022). "Among invasive breast carcinoma, no alteration in NTN4 was identified." (PMID 35732855, 2022).
ischemia (1 paper, 2016). A hypoperfusion of the BLOOD through an organ or tissue caused by a PATHOLOGIC CONSTRICTION or obstruction of its BLOOD VESSELS, or an absence of BLOOD CIRCULATION. "Using Ntn-4−/− mice, we demonstrate that differential expression of netrin-4 plays a role in pathophysiology of neovascularization and influences ischemia related but not inflammatory neovascularization." (PMID 26732856, 2016).
lung fibrosis (1 paper, 2025). "Genes prioritised by functional evidence at these signals included MUC1, which encodes a large transmembrane glycoprotein and known biomarker of lung fibrosis, and NTN4 encoding Netrin-4 whose known roles include angiogenesis." (PMID 39974050, 2025).
metastatic melanoma (1 paper, 2016). A melanoma that has spread from its primary site to another anatomic site. "Our results show that PXDN, NTN4 and GLIS3are overexpressed in metastatic melanoma clinical specimens." (PMID 27172792, 2016).
osteoarthritis (1 paper, 2024). A noninflammatory degenerative joint disease occurring chiefly in older persons, characterized by degeneration of the articular cartilage, hypertrophy of bone at the margins and changes in the synovial membrane. "Therefore, these factors were not considered confounders, and the observed differences in NTN4 expression across K/L grades are likely related to the severity of osteoarthritis itself." (PMID 39518922, 2024).
peripheral nerve injury (1 paper, 2021). Injury to a peripheral nerve. "Our findings suggest that Netrin-4 induced by peripheral nerve injury causes neuropathic pain via Unc5B." (PMID 33914819, 2021).
retinal diseases (1 paper, 2021). "The findings presented in this study pave the way to systematic translational approaches to unveil the role of NTN4 in degenerative and inflammatory-related retinal diseases such as DR and to evaluate the potential of NTN4 as a biomarker for the severity/progression of DR." (PMID 33923095, 2021).
rotator cuff tear (1 paper, 2025). "While our model provides insight into the temporal dynamics and mechanistic role of NTN4 in an acute rotator cuff tear setting, it is important to recognize that most clinical cases involve chronic degenerative tendon injuries rather than acute trauma." (PMID 40688916, 2025). "Together, these findings indicate that, following rotator cuff tear, an early TNF-α-driven increase in NTN4 may serve as a key intermediary that prolongs MMP-3-mediated matrix degradation, thereby linking acute inflammation to sustained tendon remodeling." (PMID 40688916, 2025).
tendon disease (1 paper, 2025). "To date, there are no published reports demonstrating elevated NTN4 expression in human tendon disease samples." (PMID 40688916, 2025).
testicular germ cell tumor (1 paper, 2020). A germ cell tumor arising from the testis. "The expression of NTN1 and NTN4 was related to radiation therapy and pathologic stage in Testicular Germ Cell Tumors (TGCT)." (PMID 32251318, 2020).
tumor (43 papers, 2006 to 2026). "In luminal subtype, NTN4 expression level was negatively associated with tumor purity (r = − 0.258, P = 9.80e−10), whereas positively associated with B cells, CD8+ T cells, CD4+ T cells, macrophages, neutrophils, and DC." (PMID 35732855, 2022). "Having assessed the expression and the interaction of NEO1 and NTN4 in both NB tumors and cell lines, we next decided to evaluate the potential contribution of the NEO1/NTN4 complex signaling in a variety of processes associated with tumor progression." (PMID 28038459, 2017). "These netrin-4–involved inhibitory effects are associated with decreased tumor cell proliferation and increased tumor cell apoptosis." (PMID 25853509, 2015). "Notably, alteration in NTN4 expression has been implicated in a range of human malignancies and has been proposed as a prognostic marker in some cancers, where it was reported to inhibit angiogenesis and delay tumor development." (PMID 37736464, 2023). "Additionally, the estimation of tumor number and volume, and its association with NTN4 levels might be useful in further uncovering the prognostic value of NTN4 value in HCC patients." (PMID 37736464, 2023). "NTN4 has been extensively studied in the context of axonal guidance, angiogenesis, and tumor biology, with its crystal structure elucidated to reveal insights into its molecular interactions." (PMID 40136644, 2025). "In contrast to Netrin-1, Netrin-4 serves as a tumor suppressor in CRC by inhibiting angiogenesis, hinders primary tumor growth, liver and lung metastases." (PMID 38081962, 2024). "In cancer, for example, NTN4 has been shown to contribute to tumor progression by modulating the tumor microenvironment." (PMID 39518922, 2024). "Recombinant human NTN4 protein (rhNTN4) was used to treat EC cells, and then the tumor-sphere formation capability was analyzed to clarify the function of secreted NTN4 in regulating cancer stemness." (PMID 38164180, 2024). "further found that high expression of NTN4 inhibited the primary tumour growth and recurrence of colorectal xenografts in nude mice, while also inhibiting the tumour number and liver metastasis volume of the orthotropic liver metastasis model." (PMID 38546656, 2024). "We also found an inverse expression between miR-210 and NTN4 in cancer cells after coculture or in tumor xenografts." (PMID 38175202, 2024). "Related experiments showed that NTN1 and NTN4 were highly expressed in NB cell lines and tumour tissues and were positively correlated with poor prognosis." (PMID 38546656, 2024). "Among the netrin family proteins, netrin-4 (NTN4) has been identified in tumor cells, fibroblastic cells, and endothelial cells." (PMID 39518922, 2024). "CXCL14 (log2FC = − 2.73, adjusted p-value < 0.001) and NTN4 (log2FC = − 1.89, adjusted p-value < 0.001) were differentially expressed in stromal and tumor regions, respectively." (PMID 39135097, 2024). "We subcutaneously injected 786-O cells transfected with pc-Vector or pc-NTN4 into nude mice and observed tumor growth for four weeks." (PMID 37345154, 2023). "Western blotting analysis confirmed that NTN4 overexpression downregulated β-catenin, Vimentin, and Bcl-2 expression in the tumor tissues." (PMID 37345154, 2023). "At low physiological ligand concentrations, NTN4 has been observed to promote cell survival and migration, whereas, at high concentrations, it behaves as an anti-angiogenic agent to inhibit tumor growth." (PMID 37736464, 2023). "Findings from experimental models of primary tumor and metastasis in mice indicated that overexpression of NTN4 reduced the recurrence of the tumor as well as metastasis after surgical resection." (PMID 37736464, 2023). "Recent evidence has suggested that NTN4 acts as a tumor suppressor in a range of malignancies affecting the breast, pancreas, prostate, cervical, and colon." (PMID 37736464, 2023).
tumor (continued). "Our established in vivo models of ccRCC proliferation and lung metastasis demonstrated NTN4’s inhibitory effects on tumor growth and metastasis." (PMID 37345154, 2023). "Netrin-4 (NTN4) is a member of the family of laminin-related secreted glycoproteins, which dynamically regulate angiogenesis based on the tumor microenvironment." (PMID 37736464, 2023). "Further studies are warranted to understand if NTN4 has therapeutic potential against tumor growth and metastasis in HCC." (PMID 37736464, 2023). "The group of mice injected with pc-NTN4 transfected cells showed a statistically significant reduction in tumor size and weight compared with the control group." (PMID 37345154, 2023). "In the TIMER, NTN4 mRNA expression levels were significantly related to 33 out of 45 immune cell markers after adjustment for tumor purity." (PMID 35732855, 2022). "Consistently, NTN4 mRNA expression level in BC tumor was significantly higher than in normal tissue (P < 0.001)." (PMID 35732855, 2022). "Based on TIMER, relationships of NTN4 expression with tumor immune invasion and immune cell surface markers were evaluated." (PMID 35732855, 2022). "Meanwhile, expression of NTN4 in tumor was significantly lower than those in adjacent tissue in unpaired and paired samples." (PMID 35732855, 2022). "NTN4 promoter methylation level was significantly higher in primary tumor than in normal tissue (P < 0.001)." (PMID 35732855, 2022). "The physiological implications of this ability are beginning to be appreciated; recent work has demonstrated that netrin-4 levels are a key determinant of basement membrane stiffness with knock-on effects to cell behavior and tumor metastasis." (PMID 34456976, 2021). "In tumor cells, NTN4 labels in a distinctive punctuated pattern, suggestive of strong expression in secretory organelles, observations that need to be further defined." (PMID 30160193, 2019). "Within the tumor cells, NTN4 expression is located in the cytoplasm surrounding the nucleus (arrowhead)." (PMID 30160193, 2019). "Given the pronounced role for NTN4 in tumor biology, the expression levels and regulation of NTN4 isoforms are of particular interest." (PMID 30923634, 2019). "Here, we show that NTN4 is broadly expressed in tumor, stroma and blood vessels of NB patient samples." (PMID 30160193, 2019). "In vivo analysis, using the chicken embryo chorioallantoic membrane (CAM) model, showed that NEO1 and endogenous NTN4 are involved in tumor extravasation and metastasis." (PMID 28038459, 2017). "By contrast, MYCN amplified tumor samples have more NTN4 expression, which is in line with the expression data observed in NB cell lines analyzed in this work." (PMID 28038459, 2017). "Recent studies have suggested a role for NTN4 in regulating metastasis, angiogenesis and tumor growth." (PMID 27172792, 2016). "Since tumour growth, in particular, depends on oxygen-driven blood vessel growth, we suggest that the netrin-4-dependent regulation of blood vessel stability explains these observations." (PMID 26732856, 2016). "NTN4 is a member of the netrin family that are secreted chemotropic guidance cues with roles in embryogenesis and tumor development." (PMID 27172792, 2016). "The levels of Ntn4 in the sera of the tumor patients were significantly higher than those of the normal samples (n = 52, p < 0.0001)." (PMID 25909166, 2015). "Ntn4 expression was significantly higher in the tumor tissues (up panels) compared with adjacent tissues (down panels)." (PMID 25909166, 2015). "Netrin-4 (Ntn4) is a laminin-related secreted molecule found to regulate tumor progression and metastasis." (PMID 25909166, 2015). "Immunohistochemical analysis of tumor sections with an antibody specific for desmin, a marker of perivascular cells, was used to evaluate the effect of Netrin-4 transfection on the tumor vasculature at the cellular level." (PMID 24472220, 2014).
tumor (continued). "In this model, the main source of Netrin-4 is provided by the transfected PC3 tumor cells, which secrete the protein." (PMID 24472220, 2014). "Here, we show that Netrin-4 overexpression improved tumor blood vessel structure and increased VSMC coverage." (PMID 24472220, 2014). "Netrin-4 overexpression in a model of subcutaneous PC3 cell xenograft increased the recruitment of mural cells to tumor vessels." (PMID 24472220, 2014). "All these data suggest that inactivation of netrin-1 and overexpression of netrin-4 can be useful in tumor therapy." (PMID 25143950, 2014). "On the other hand, netrin-4 overexpression decreased tumor recurrence and metastases after surgical resection in mouse models." (PMID 25143950, 2014). "Double Desmin/CD31 immunostaining of tumor sections shows that Netrin-4 overexpression in PC3 cancer cells increases coverage of tumor vasculature." (PMID 24472220, 2014). "Taken together, our in vivo findings suggest that Netrin-4 overexpression induces tumor vessel maturation by recruiting more perivascular cells." (PMID 24472220, 2014). "We previously showed that Netrin-4 overexpression in PC3 cancer cells delayed tumor growth in a model of subcutaneous xenograft by reducing tumor vessel density." (PMID 24472220, 2014). "Ex vivo drug testing revealed a striking response: the mTOR inhibitor Sapanisertib induced extensive tumor necrosis and was associated with near-complete depletion of ALDH1A1+ and NTN4+ states, accompanied by strong stress/apoptosis signatures and reduced endothelial cells." (PMID 42070010, 2026). "Netrin-4 was also shown to delay colorectal cancer progression by inhibiting tumor angiogenesis." (PMID 38375479, 2024). "However, most of these studies focused on the paracrine effects of NTN4 on tumor stromal cells, including fibroblasts, macrophages, lymphocytes, and endothelial cells." (PMID 38164180, 2024). "Meanwhile, the stiffness of BM could influence tumor invasion through a protein called netrin-4 (Net4)." (PMID 36816030, 2023). "Conversely, NTN4 is a tumor growth inhibitor in primary and metastatic colorectal tumors." (PMID 37345154, 2023). "Therefore, overexpression of NTN4 attenuates tumor migration and invasion and provides a novel direction for ccRCC treatment." (PMID 37345154, 2023). "NTN4 likely plays an essential role in controlling tumor growth and metastasis." (PMID 37736464, 2023). "These stiffness effects might be a key determinant of tumour invasion potential; softer tissues with higher netrin-4 to LM ratio display a resistance to metastasis formation." (PMID 36355367, 2022). "NTN4 protein expression was verified by IHC in adjacent tissue and tumor tissue." (PMID 35732855, 2022). "Moreover, netrin-4-induced changes to BM stiffness is a strong predictor of tumour metastasis and patient outcome in numerous cancers including breast cancer." (PMID 35231053, 2022). "The AUC of NTN4 was 0.764, suggesting that NTN4 could serve as a biomarker to distinguish BC from non-tumor tissue." (PMID 35732855, 2022). "Probably, tumor cells are attracted to endothelial capillaries as they disseminate and, NTN4, produced as a chemotactic molecule in this permissive substrate, might facilitate their migration." (PMID 30160193, 2019). "Particularly, we evaluated NTN4 presence in tumor cells, stroma and blood vessels." (PMID 30160193, 2019). "In both cancers, it has been shown that NTN4 has a role in the migration and/or metastasis of tumor cells, without specifying the mechanism associated with these functions." (PMID 30160193, 2019). "Whether the differences in experimental conditions could explain these contradictory results, or whether NTN4 should be blocked or stimulated is based on in what tissue the tumor occurs, has to be determined with further analysis." (PMID 30923634, 2019).
tumor (continued). "After examining the potential role of endogenous NEO1 and NTN4 participating in apoptosis and cell migration, we wanted to ascertain whether they also participate in primary tumor formation and metastasis in vivo." (PMID 28038459, 2017). "Combined, these findings suggest a possible biological role for NTN4 in tumor metastasis." (PMID 28038459, 2017). "Considering that NEO1 is involved in neuronal cell migration, we aimed to address whether this function was relevant in the tumor context and if it was dependent of its ligand NTN4." (PMID 28038459, 2017). "Using transwell chemotaxis assays, we examined the function of NEO1 in sensing and guiding tumor NB cells, and analyzed whether NTN4, a known chemotactic molecule, influenced this process." (PMID 28038459, 2017). "In a tumor model, netrin-4 overexpression was shown to inhibit tumor growth." (PMID 26732856, 2016). "Elevated Ntn4 was detected in both tumor tissues and serum samples of GC patients and suggested a relatively poor survival, indicating Ntn4 may be used as a potential non-invasive biomarker for diagnosis and prognosis of GC." (PMID 25909166, 2015). "Like Ntn1, Ntn4 is able to stimulate tumor proliferation and angiogenesis." (PMID 25909166, 2015). "Importantly, we initially identified the high expression of Ntn4 in both tumor tissues and serum samples of GC patients, which was negatively correlated with survival rate and positively with severity of pathological stages of GC." (PMID 25909166, 2015). "Importantly, Ntn4 level was significantly increased in 82 tumor tissues (p = 0.001) and 52 serum samples (p < 0.0001) from GC patients and positively correlated with Neo expression (p = 0.003)." (PMID 25909166, 2015). "Moreover, the high Ntn4 expression was detected in 71% (34/45) tumor samples with stage III and stage IV but only 12% (12/37) with Stage I and II." (PMID 25909166, 2015). "In addition, netrin-1 or netrin-4 overexpression in tumor cells delays tumor angiogenesis in various animal models." (PMID 25853509, 2015). "These Netrin-4 anti-tumor properties were attributed to direct effects on endothelial cells." (PMID 24472220, 2014). "Overexpression of Netrin-4 may also mediate tumor vascular normalization through its actions on the vascular basement membrane and inhibitory effects on EC." (PMID 24472220, 2014). "As observed in a recent model of corneal neovascularization, Netrin-4 may also induce tumor blood vessels normalization through down-regulation of VEGF." (PMID 24472220, 2014). "We previously reported that Netrin-4 overexpression in PC3 cells delayed tumor uptake and growth." (PMID 24472220, 2014). "However, conflicting arguments have been made about the function of NTN4, as it has been observed to promote cell proliferation in various tumor cell types." (PMID 24780490, 2014). "The in vivo analysis also suggests that maturation of the tumoral vasculature induced by Netrin-4 may be responsible for the reduced tumor growth in vivo." (PMID 24472220, 2014). "Moreover, double immunostaining with the endothelial marker CD31 showed colocalization with desmin staining indicating that Netrin-4 enhanced the recruitment of perivascular cells on tumor EC." (PMID 24472220, 2014). "Recent studies have reported that Ntn4 could bind to Neo to modulate tumor angiogenesis." (PMID 25909166, 2015). "Also, Ntn4 can act as a regulator of tumor progression and metastasis." (PMID 25909166, 2015). "Besides the central nervous system, netrin-4 has been shown to regulate epithelial branching and morphogenesis in the lung, pancreas, salivary gland branching, lymphangiogenesis, angiogenesis, and tumor growth." (PMID 25143950, 2014). "These contain known cancer-testis antigen genes (MEGA5, MEGA1, TEX15, PNMA5 and ROR1) and a number of new candidate genes (PAX2, NTN4, NTNG2 and PDE10A), these genes can be used as tumour markers or potential therapeutic targets with some clinical value." (PMID 37994961, 2023).